RN7SL125P (RNA, 7SL, cytoplasmic 125, pseudogene)
Gene: Miscellaneous RNA gene on chromosome 17 (48,765,554 to 48,765,847, reverse strand). Ensembl gene ENSG00000244514.
Homologues: Orthologues: chimpanzee Metazoa_SRP (99% identical), macaque Metazoa_SRP (92% identical). Paralogues in human: RN7SL1 (87% identical), RN7SL2 (86% identical), RN7SL3 (85% identical), RN7SL597P (83% identical), RN7SL566P (83% identical), RN7SL712P (83% identical), RN7SL655P (82% identical), RN7SL230P (82% identical), RN7SL45P (82% identical), RN7SL516P (82% identical), RN7SL660P (82% identical), RN7SL322P (82% identical), and 705 more.